IL1B (interleukin 1 beta)
Diseases named in the same sentence as IL1B in open-access papers (continued):
Sharing a sentence is not in itself a finding about the gene and the disease.
periodontitis (continued). "Another study found that chemerin and inflammatory cytokines such as IL‐1β, IL‐6, and TNF‐α were notably higher in the serum of patients with chronic periodontitis than those in the control group, (periodontally healthy/gingivitis)." (PMID 39494478, 2024). "Enhanced transcriptional and inductive IL-1β and MMP-7 expressions in periodontitis-affected gingiva can eventually potentiate and complement the Td-dentilisin-mediated microbial-dependent activation of the degranulated latent proMMP-8 to aMMP-8." (PMID 38786309, 2024). "A clinical report showed that periodontitis patients have higher levels of NLRP3, ASC, caspase 1 and IL-1β in serum and saliva than healthy controls." (PMID 38596842, 2024). "Similar to the mRNA expression results, enhanced protein expression of IL1β, SRGN, CXCR1, and PTAFR was observed in the periodontitis group." (PMID 38491529, 2024). "A recent systematic review highlights several biomarkers, including macrophage inflammatory protein-1 alpha (MIP-1α), IL-1β, IL-6, and MMP-8 (matrix metalloproteainase-8), as promising indicators for diagnosing periodontitis." (PMID 39917647, 2024). "The body responds to periodontitis by producing inflammatory cytokines like TNF-α, IL-1β, and IL-6, which play crucial roles in the disease's progression." (PMID 39044527, 2024). "Previous studies regarding serum levels of IL-1β and TNF-α in periodontitis presented diverging results and were based on small cohorts with different methods for protein assessment, making comparisons with our results challenging." (PMID 39101637, 2024). "Increased plasma levels of IL-1β, IL-6, TNF-α, CRP, MMP-8, and MMP-9 have been observed in patients with periodontitis." (PMID 38672972, 2024). "Specifically, IL-1β, TNF-α, IL-6, and RANKL levels were reduced after dietary supplementation with n-3 PUFA as an adjunctive therapy for periodontitis." (PMID 39661860, 2024). "Specifically, combinations such as MMP-8 with IL-1β, IL-1β with IL-6, or MMP-8 with IL-6 correctly identified 78%–81% of patients with periodontitis and excluded 85%–88% of non-periodontitis participants." (PMID 39554809, 2024). "Meta-analysis performed for salivary biomarkers showed the highest sensitivity for the diagnosis of periodontitis for IL-1β (77.8%) and MMP-8 (72.5%), and the highest specificity for MMP-9 (81.5%) and IL-1β (78%)." (PMID 39684335, 2024). "CXCL1, CXCL3, CXCL8, CSF3, IL1A, IL1B, and IL1RN all increased in JKs in periodontitis as predicted by our atlas/DEG analyses; alternatively, SKs were relatively less active compared to JKs." (PMID 38876998, 2024). "Interleukin-1 beta (IL-1β), sclerostin, osteoprotegerin (OPG), and interleukin-34 (IL-34) emerged as significant biomarkers in GCF, and they were mainly from periodontitis and osteoporosis." (PMID 39410587, 2024). "A more comprehensive evaluation of additional combinations of periodontitis biomarkers, beyond MMP-8 with IL-1β and IL-6, is warranted, along with the development of more sensitive biomarker assays." (PMID 39554809, 2024). "The findings of this study indicate that there is a significant positive correlation between salivary IL-1β, IL-18, and GSDMD levels and clinical periodontal parameters in patients with periodontitis, as well as LDL levels in patients with ASCHD." (PMID 39071510, 2024). "In contrast, the injection of anandamide in rats with experimental periodontitis significantly reduced TNF-α and IL-1β levels compared with animals treated with saline and the antagonists, AM251 and AM630." (PMID 39065590, 2024). "They concluded that an upsurge of pro-inflammatory interleukins i.e. interleukin-1 alpha (IL-1α), IL-1β, interleukin-12 (IL-12), and IL-6 along with TNF-α, found in periodontitis." (PMID 38196480, 2024). "Treatment of periodontitis effected IL-6, LDL, HDL, TC, TG and SBP with moderate certainty of evidence while the certainty of evidence on CRP, IL-1β, TNF-α, DBP and FMD was low." (PMID 38877442, 2024).
periodontitis (continued). "The increased mRNA expression of IL-1β and IL-6 in the PBS group suggested the activation of M1 macrophages and an abundance of inflammatory cytokines in periodontitis." (PMID 39076893, 2024). "Specifically, we observed that IL-1β, SRGN, CXCR1, and PTAFR exhibited significant upregulation at both the RNA transcript and protein translation levels in periodontitis patients compared to healthy periodontal patients." (PMID 38491529, 2024). "In the present study, elevated levels of IL-1β, IL-6, and TNF-α were observed in the periodontitis group, indicating an inflammatory response mediated by inflammatory cells during disease progression." (PMID 38919285, 2024). "The results revealed that the expression of NLRP3, IL‐1β, IL‐18, IL‐6, and TNF‐α was upregulated by F. nucleatum and its OMVs in rats with periodontitis." (PMID 39475060, 2024). "Patients affected by gingivitis and periodontitis will have proinflammatory cytokines like TNF-α and IL-1β in their gingival tissue and gingival crevicular fluid." (PMID 38978754, 2024). "Inflammatory cytokines, including IL-1β, IL-6, tumor necrosis factor-alpha, and chemokine (C-C motif) ligand 2 (CCL2), play a crucial role in the inflammatory response of periodontitis." (PMID 38560458, 2024). "The combination of MMP-8, IL-1β, IL-6, and MIP-1α has shown promise in distinguishing between gingivitis and periodontitis, although based on a smaller study sample." (PMID 39554809, 2024). "CBD administered in animals subjected to experimental periodontitis and in cells stimulated by LPS from P. gingivalis reduced the levels of cytokines such as RANK, RANKL, TNF- α, IL-1β, IL-6, IL-12 p40, and IL-8." (PMID 39065590, 2024). "In saliva, combinations of IL-1β, IL-6, and MMP-8 have superior properties for the detection of periodontitis." (PMID 39684335, 2024). "The analysis revealed simultaneous significant upregulation of IL1β, SRGN, CXCR1, FGR, ARHGEF2, and PTAFR in all six periodontitis-related datasets." (PMID 38491529, 2024). "The reduction of IL-1β, TNF-α, IL-6, and RANKL levels after dietary supplementation with n-3 PUFA as an adjunctive therapy for periodontitis was the most prevalent among the reviewed studies." (PMID 39661860, 2024). "Specifically, macrophages derived from gingival tissue of periodontitis individuals exhibited pro-inflammatory phenotype by highly expressing NLRP3, an inflammasome-mediating IL-1β production." (PMID 39737182, 2024). "C: Systemically and periodontally healthy control group, CP: chronic periodontitis group, ALP: alkaline phosphatase, OSC: osteocalcin, sRANKL: soluble receptor activator of nuclear factor-kappaB, IL-1β: interleukine-1β, TNF-α: tumor necrosis factor-α." (PMID 38646303, 2024). "The ROC curves indicated a high accuracy of salivary IL-1β, IL-18, and GSDMD levels as biomarkers of periodontitis and CHD, with an AUC of 1.0 for groups P, AS-C, and AS-P (P < 0.0001)." (PMID 39071510, 2024). "The systemic inflammatory–oxidative effects of periodontitis and MetS were biochemically evaluated using the serum TNF-α level, IL-1β/IL-10 ratio, and oxidative stress index (OSI: TOS/TAS)." (PMID 39590401, 2024). "For example, research indicates that using a combination of periodontal pathogens like Porphyromonas gingivalis and salivary biomarkers such as interleukin-1β (IL-1β) and prostaglandin E2 (PGE2) can aid in predicting chronic periodontitis in older individuals." (PMID 39014403, 2024). "In another induced periodontitis in a diabetic rat experiment, Cu reduced the infiltration of PMN and monocytes, the degradation of periodontal collagen fibers—and decreased IL-1β, IL-6, TNF-α MMP-9 and MMP-2, MMP-8 levels." (PMID 38793109, 2024). "By employing IL-1β and TNF-α antagonists or knocking down the IL-1 receptor and TNF receptor, alveolar bone resorption in mice with experimental periodontitis was also decreased (Assuma, Oates, Cochran, Amar and Graves, 1998; Graves and Cochran, 2003)." (PMID 38347915, 2024).
periodontitis (continued). "Unexpectedly, GCF IL-1β and TNF-α levels were higher in T1DM periodontitis patients compared to T2DM periodontitis ones." (PMID 39000406, 2024). "According to this study, salivary IL-1β and MMP-8 are potential biomarkers to identify periodontitis and gingivitis." (PMID 38086426, 2024). "Based on previously published data, IL-1β, IL-6 and TNF-α were chosen, in order to mimic the inflammatory environment that can be found in periodontitis." (PMID 39252697, 2024). "This study evaluated changes in inflammatory markers within GCF, including TNF-α, IL-1β, IL-6, IL-8, hs-CRP, ICAM-1, HMGB1, and PGE2, before and after treatment in patients with osteoporosis and periodontitis." (PMID 39686428, 2024). "It has been well documented that NF-kB activation, which is pivotal in periodontitis and cancer-related inflammation, induces the expressions of pro-inflammatory cytokines, including TNF-α, IL-1β, IL-6, and IL-8, in different cell types." (PMID 38612423, 2024). "Increased levels of salivary IL-1β, IL-6, and MMP-8 were observed in individuals with periodontitis." (PMID 39410587, 2024). "A rat model of experimentally generated periodontitis was used to assess the impact of PRP preparation on the expression of the osteoclastogenic and pro-inflammatory markers respectively; RANKL and IL-1β." (PMID 40952876, 2024). "IL-1β, IL-6, TNF-α and IFN-γ have been identified as key players in the pathogenesis of periodontitis." (PMID 38002398, 2023). "The machine-learning method, RF, was performed to create an ideal model to predict the occurrence of periodontitis and selected five hub PRGs (CHMP2B, GZMB, ZBP1, IL1B, and IRF1)." (PMID 37090158, 2023). "In RA and periodontitis, adaptive and innate immune cells promote the release of proinflammatory cytokines (TNF-α, IL-6, IL-17A, IL-1β, RANKL), which have an important role in establishing and maintaining inflammation." (PMID 37217496, 2023). "When compared to healthy controls, patients with chronic periodontitis had salivary levels of NLRP3, ASC, and IL-1β that were 2.94 times higher, 1.70 times higher, and 1.53 times higher, respectively." (PMID 36769328, 2023). "There was a higher prevalence of stage III periodontitis and severe OSA, as well as higher levels of periodontal parameters (PI and BOP), and expression of IL-1β and IL-6 in saliva and IL-6, IL-17A, and IL-33 in GCF, in patients with periodontitis and OSA." (PMID 36967976, 2023). "A clinical study has reported significantly higher levels of IL-1β and TNF-α in the gingival crevicular fluid of individuals with periodontitis and peri-implantitis compared to both healthy subjects and those with healthy implants." (PMID 37626627, 2023). "The expression levels of four inflammatory cytokines, IL-6, IL-10, IL-8, and IL-1β, were evaluated in salivary EXO-NET EVs of non-periodontitis and periodontitis patients using ELISA." (PMID 39697803, 2023). "The results of this study demonstrate cytokine dynamics of IL-1β, TNF-α, and IL-10 in periodontitis, especially in older people." (PMID 37623272, 2023). "The levels of IL-6, IL-1β, TNF-α, and IFN-β secreted under the influence of P. gingivalis were lower in the StingGt periodontitis mice than in the WT periodontitis mice (p < 0.05)." (PMID 37405166, 2023). "In this study, we aimed to clinically analyze the periodontal status and the cytokine levels of IL-1β, TNF-α, and IL-10 in older people and adults with periodontitis." (PMID 37623272, 2023). "Some studies assessed the influence of SRP on clinical parameters and IL1β, IL8, and MMP-8 levels in GCF in patients with chronic periodontitis." (PMID 38249256, 2023). "Based on the literature data available, we aimed to delineate the roles of IL-1β and TNF-α in the pathogenesis of periodontitis and AD." (PMID 36915108, 2023). "Subsequently, the inflammatory cytokines expression levels (interleukin-IL-6, IL-1β, IL-8, and IL-10) in EXO-NET EVs were measured for non-periodontitis and periodontitis." (PMID 39697803, 2023).
periodontitis (continued). "Initially, to ensure the reliability of the samples, inflammatory cytokines including IL-1β, IL-6, and TNF-α of each group were evaluated by RT-qPCR, all of which are significantly upregulated in periodontitis." (PMID 37261283, 2023). "In conclusion, our results demonstrated, through meta-analytic methods with 1,983 participants from 9 studies, that IL-6, nitric oxide, IL-1B, TNF-α and osteoprotegerin are among the most present biomarkers in patients with periodontitis." (PMID 37026605, 2023). "Periodontal bacterial and related endotoxins, present during periodontitis, trigger systemic inflammation, as revealed by the increased levels of CRP, TNFα, IL-1β, and IL-6 in the serum of patients." (PMID 37895050, 2023). "Elevated levels of IL‐1β, IL‐6, and TNF‐α have been detected in inflamed gingival tissues of patients with periodontitis, which contributes to tissue destruction and the progress of periodontitis." (PMID 37506160, 2023). "In vivo test using a rat periodontitis model treated with glycyrrhizin revealed the downregulation of HMGB1, IL-6, and IL-1β in the gingival crevicular fluid and periodontal tissue." (PMID 37396128, 2023). "A recent systematic review and meta-analysis suggests MIP-1α IL-1β, IL-6, and MMP-8 as highly sensitive salivary markers of periodontitis." (PMID 38068492, 2023). "First, IL-1β and TNF-α are elevated in periodontitis patients, and thus are considered representative inflammatory cytokines in this background." (PMID 37626627, 2023). "Overall, mean IL-1β detected in the saliva of participants with CHD (AS-P, 194.15 pg/mL; AS-C, 123.29 pg/mL) and periodontitis alone (P, 78.43 pg/mL), were significantly higher than the control group (C, 5.94 pg/mL) (F value = 17.97, p < 0.001)." (PMID 37974134, 2023). "In addition to IL-1β, RANK-L could be considered a combined diagnostic biomarker for periodontitis." (PMID 36769650, 2023). "In patients with severe periodontitis, the serum concentrations of pro‐inflammatory cytokines such as IFN‐γ, IL‐2, TNF‐α, and IL‐1β are much higher than that of healthy controls, which is also observed in gingival tissue biopsies." (PMID 37647428, 2023). "The expression of IL‐1β, GSDMD, and Synoviolin in peripheral blood mononuclear cells from patients with periodontitis was determined." (PMID 37506160, 2023). "Obese subjects with periodontitis are characterized by an increase in pro-inflammatory cytokines (IL-1β, IL-6, TNF), also in blood, and also in gingival fluid samples, compared to normo-weighted subjects with periodontitis." (PMID 37894804, 2023). "This study aimed to clinically analyze the periodontal status and cytokine levels of IL-1β, TNF-α, and IL-10 in older people and adults with periodontitis." (PMID 37623272, 2023). "HGFs stimulated with pathogens have been reported to upregulate the gene expression of the pro-inflammatory cytokines IL-6, IL-1β, IL-8, and TNF-α, which facilitates the inflammatory cascade in periodontitis." (PMID 37110385, 2023). "The upregulation of IL-1β and TNF-α levels in the gums of aged mice and Pg-injected mice led us to next delineate the roles of these two cytokines in the pathogenesis of periodontitis and AD." (PMID 36915108, 2023). "In the present study, we found that there was upregulated mRNA expression of IL‐1β and GSDMD in PBMCs, as well as an increased serum level of IL‐1β in patients with periodontitis, suggesting the activation of inflammasome in periodontitis." (PMID 37506160, 2023). "A recent clinical study reported that patients with periodontitis show elevated serum and saliva NLRP3 concentrations, and elevated NLRP3, ASC, and IL-1β concentrations in saliva are proposed biomarkers for periodontal clinical status." (PMID 35567665, 2022). "Another clinical study showed that saliva samples from a periodontitis group had significantly higher levels of NLRP3 and IL-1β than controls." (PMID 35628185, 2022).
periodontitis (continued). "In contrast, IL-6, IL-1β, and TNF-α exhibited strong staining in the periodontitis group, suggesting that the periodontitis model had been well established." (PMID 35340409, 2022). "In addition, other inflammatory mediators in periodontitis, such as IL-1β, IL-6, tumor necrosis factor-α, etc., can be secreted into the blood to activate the systemic immune response, which may lead to tissue destruction in other organs to release DAMPs-derived cfDNA." (PMID 36498477, 2022). "P. gingivalis infection successfully induces the loss of alveolar bone, significantly activates osteoclasts, and increases the expression of IL-17, IL-1β, and RANKL in periodontitis." (PMID 36050950, 2022). "While in the study of periodontitis, glyburide can prevent NLRP3 inflammasome activation and decrease IL-1β release in periodontal pathogen-induced inflammation." (PMID 36185327, 2022). "Our results indicated that DhHP-6 has therapeutic effects in periodontitis by reducing the levels of the inflammatory factors TNF-α and IL-1β in HGFs sensitized by LPS and reducing the cellular inflammatory response." (PMID 36546940, 2022). "We found that the mRNA expression of IL-1β, IL-6, and TNF-α in the periodontitis group was, respectively, 2.59-, 5.23-, and 2.29-fold than that of the control group." (PMID 35340409, 2022). "However, the IL-1B (rs1143634) SNP could not be found as a risk predictor for chronic periodontitis." (PMID 36429405, 2022). "The qRT-PCR results revealed upregulation of IL-1β, IL-6 and ALOX5 in the periodontitis group and further upregulation in the periodontitis with T2DM group, while the expression of NFE2L2 was the opposite." (PMID 36248844, 2022). "The salivary levels of miR-1246, IL-1β, IL-6, IL-17, TNF-α, MMP-1, MMP-8, and TIMP-1 and the periodontal indexes PLI, GI, PD, and AL in the chronic periodontitis group were significantly higher than those in the healthy control (P < 0.05)." (PMID 35942384, 2022). "Compared with the control group, the mRNA expression levels of IL-1β, IL-6 and ALOX5 were increased in the periodontitis group and further increased in the periodontitis with T2DM group." (PMID 36248844, 2022). "A recent study demonstrated that periodontitis enhanced the levels of proinflammatory cytokines (TNF-α and IL-1β), oxidative stress (MDA), and proteases (MMP-8, MMP-9, and cathepsin D) in rat kidneys, while melatonin suppressed them significantly." (PMID 36498871, 2022). "Proinflammatory cytokines IL-1β, IL-6, and TNF-α are present in osteoclast precursor cells and mature osteoclasts, and it mediates bone resorption in periodontitis." (PMID 35757444, 2022). "Periodontitis patients demonstrated activation of the NLRP3, which governs the conversion of pro-IL-1β into its active form." (PMID 36289921, 2022). "These authors presented that single nucleotide polymorphisms in the IL-1α, IL-1β, IL1RN, IL-6, IL-10, TNF-α, transforming growth factor β1 (TGF-β1), interferon γ (IFN-γ) and vitamin D receptor (VDR) may be associated with susceptibility to chronic periodontitis." (PMID 35453197, 2022). "Patients with periodontitis exhibit an elevated level of systemic pro-inflammatory mediators, which include CRP, TNFα, IL-1β, IL-6, as well as increased neutrophil numbers in the blood." (PMID 35874771, 2022). "In periodontitis, inflammation-inducing factors, such as TNF-α, IL-1β, and IL-6, are secreted from PDL cells due to bacterial endotoxin release, causing periodontal inflammation and infection." (PMID 36145616, 2022). "In models of periodontitis, fucoxanthin was shown to inhibit the promotion of osteoclast differentiation and reduce TNF, IL-1β, and IL-6 levels in blood." (PMID 36501023, 2022). "In Pg-LPS-induced periodontitis, macrophages regulate the inflammatory response by producing a variety of proinflammatory mediators such as TNF-α, IL-6, and IL-1β." (PMID 35340409, 2022).